GCG (glucagon)
Diseases named in the same sentence as GCG in open-access papers (continued):
Sharing a sentence is not in itself a finding about the gene and the disease.
Hypoglycemia (continued). "Treatment of hypoglycemia is still based on administration of carbohydrates (oral or parenteral according to the level of consciousness) or, especially in out-of-hospital environments, of glucagon by intramuscular (IM) or subcutaneous (SC) injection." (PMID 34638984, 2021). "V1bRs contribute to hypoglycemia/glucopenia-induced glucagon release in vivo." (PMID 34752420, 2021). "The aim of this review is to (i) summarize current knowledge on glucagon responses during hypoglycemia in normal physiology and type 1 diabetes, and (ii) review human in vivo studies investigating glucagon responses after other stimuli in individuals with type 1 diabetes and nondiabetic individuals." (PMID 34405569, 2021). "Importantly, administration of amino acids during hypoglycemia stimulates glucagon secretion in individuals with type 1 diabetes despite substantial hyperinsulinemia reflecting the presence of intact alpha cell function in response to amino acids." (PMID 34405569, 2021). "However, although this effect has been ascribed in the past to preserved insulin secretion, no studies, to our knowledge, have examined the impact of C-peptide per se on glucagon secretion in response to insulin-induced hypoglycemia." (PMID 34003799, 2021). "Moreover, when DPP-4 inhibitors block persistent glucagon oversecretion, glucagon responds normally to a drop in BG level and ameliorates hypoglycemia." (PMID 34203048, 2021). "Thus, the inappropriately intact liver glycogen stores in the setting of substantial hypoglycemia argues in favors of impaired glucagon-induced glycogenolysis in Fabp4–/– mice." (PMID 34676825, 2021). "In our study, R481 may activate an AMPK-ANS-HGP axis, whilst also increasing plasma glucagon levels to better defend against hypoglycemia." (PMID 34975743, 2021). "We investigated the role of AVP in regulating glucagon secretion in vivo during hypoglycemia." (PMID 34787082, 2021). "Insulin-induced hypoglycemia (from 8 mM to 4 mM) increased circulating glucagon levels tenfold." (PMID 34787082, 2021). "The project has been continued by Eli Lilly, a U.S. pharmaceutical company that obtained registration for IN glucagon as a powder (with beta-cyclodextrin plus dodecyl-phospho-choline as the promoter) for severe hypoglycemia in adult and adolescent insulin users in US, Canada, and Europe in 2019." (PMID 34638984, 2021). "Moreover, suppression of AMPK activity using shRNA diminishes the glucagon and adrenaline response to hypoglycemia." (PMID 34975743, 2021). "Furthermore, an attenuated suppression during hyperglycaemia and, to a lesser extent, an augmented glucagon rise during hypoglycaemia seem to be features of both insulin resistance and obesity." (PMID 33241460, 2021). "However, preserved beta-cell mass allows for normal insulin secretion and glucose tolerance, with enhanced glucagon release in response to hypoglycemia." (PMID 33619692, 2021). "Moreover, the fall in blood glucose during prolonged exercise is accompanied by a reduction in insulin and a rise in glucagon concentrations, particularly if a degree of hypoglycemia ensues." (PMID 34284060, 2021). "Early studies have shown that the intraislet blood microcirculation flows from the beta cell to the alpha cell supporting the traditional concept that alpha cell glucagon secretion is critically dependent on upstream signals from beta cells both during hypoglycemia and hyperglycemia." (PMID 34405569, 2021). "This is a scenario specific to hypoglycemia, since other stimuli, including administration of amino acids, insulin withdrawal, lipopolysaccharide exposure, exercise and even meals lead to profound glucagon responses." (PMID 34405569, 2021). "This reduced glucagon secretion during insulin-induced hypoglycemia by 60%." (PMID 34787082, 2021).
Hypoglycemia (continued). "Although often associated with hypoglycemia‐associated autonomic failure (HAAF), the absence of glucagon response to hypoglycemia is present in some people with type 1 diabetes with otherwise intact hormonal counter regulatory responses." (PMID 34405569, 2021). "In control subjects, hypoglycemia evoked a ~17 pM increase in plasma glucagon within 60 min." (PMID 34787082, 2021). "Moreover, alpha cells in the pancreas secrete glucagon when blood glucose levels are falling, as can occur with fasting and/or exercise, in order to prevent hypoglycemia (low glucose levels)." (PMID 34027090, 2021). "In the home setting, hypoglycemia was treated with glucose-rich food (n = 6) or medication (n = 3; oral glucose tablets or gel), by initiating a feed via G-tube (n = 5), or by using a glucagon injection kit (n = 1)." (PMID 32028919, 2020). "As glucagon is a counterregulatory hormone, we also explored whether glucagon was inappropriately secreted in HFD-fed mice during insulin-induced hypoglycaemia in response to an insulin tolerance test (ITT)." (PMID 32446876, 2020). "In addition, this condition should also be suspected when there is a glycemic response to glucagon at the time of hypoglycemia." (PMID 32948218, 2020). "FGF1 showed a robust glucose homeostasis profile, lowed the plasma insulin of db/db mice and did not cause hypoglycaemia and changeable plasma glucagon after chronic administration." (PMID 32979037, 2020). "However, a paracrine role of insulin in the physiologically important glucagon counterregulation of hypoglycemia seems unlikely because insulin release is basal under such conditions." (PMID 32156704, 2020). "Also, reports have documented the use of a stable form of glucagon in adults with hypoglycemia, however more clinical trials are required to prove its efficacy in children with HH." (PMID 32185602, 2020). "High-intensity interval training induced an increased oxidative capacity of skeletal muscle and blunts the rates of glucagon breakdown, which could be a possible protective effect against hypoglycemia after exercise." (PMID 32326182, 2020). "For example, hypoglycemia that results from exercise may occur even in automated closed-loop systems even when glucagon is delivered in anticipation of exercise." (PMID 32517068, 2020). "In addition to the increase of glucagon secretion triggered directly by hypoglycemia, there is a counterintuitive increase of glucagon triggered by hyperglycemia." (PMID 32132928, 2020). "Our study provides novel insights into the potential role of glucagon in preventing postprandial hypoglycemia, which may contribute to devising targeted medical or surgical interventions to prevent and manage PBH." (PMID 33424773, 2020). "Therefore, our study supports the validity of titration of glucagon in the treatment of hypoglycemia alongside the use of glucagon at a standardized dose." (PMID 33013678, 2020). "The ability of SC-alpha cells to protect against hypoglycemia and increase circulating glucagon levels in response to physiological cues may represent an avenue for therapeutic intervention in hypoglycemia." (PMID 32382023, 2020). "Severe hypoglycemia is defined as a condition with serious cognitive dysfunction, such as a convulsion and coma, requiring external help from other persons to provide glucose and glucagon or take other correction assistance." (PMID 33042005, 2020). "Disagreements regarding the KITT% model refer to the possibility of activation of a counter-regulatory response by hypoglycemia on hormones that could influence on glucose depletion, such as glucagon, catecholamines, and growth hormone." (PMID 31914140, 2020). "For many years, glucagon has been thought of as the counterregulatory hormone to insulin with a primary function of increasing blood glucose concentrations and protecting against hypoglycemia." (PMID 33333850, 2020).
Hypoglycemia (continued). "One of the proposed intrinsic pathways leading to hypoglycemia-induced glucagon secretion is a decrease in the ATP/ADP ratio, which paradoxically slightly increases KATP channel activity, leading to voltage-dependent increased activity of P/Q type calcium channels and a subsequent influx of Ca2+." (PMID 31284506, 2019). "Furthermore, the knockdown of IR in αTC1 cells reduced glucagon secretion under low glucose conditions, which indicates that glucagon hyposecretion and hypoglycemia are prolonged in diabetic state." (PMID 31357734, 2019). "They concluded that glucagon secretion in response to hypoglycemia may be impaired by chronically high levels of catecholamines." (PMID 31275775, 2019). "According to Taborsky's group, this loss of sympathetic innervation may partly explain the impaired glucagon response to insulin-induced hypoglycemia during T1DM." (PMID 31620088, 2019). "However, the increased glucagon secretion in hypoglycemia is mainly related to the sympathetic nerve." (PMID 31357734, 2019). "Exercise-induced hypoglycemia may be a result of blunted glucagon response, reduced adrenomedullary response, and diminished clearance of injected insulin." (PMID 30781593, 2019). "Reduced spending resulted from reduced professional emergency services utilization as successful treatment was more likely with IN glucagon, and therefore IN glucagon has the potential to improve hypoglycemia emergency care and reduce severe hypoglycemia-related treatment costs." (PMID 31349701, 2019). "The role of glucagon becomes crucial when blood glucose levels are low as it ensures that a sufficient amount of glucose is produced in order to avoid unconsciousness, brain damage and the other risks posed by hypoglycaemia." (PMID 31829209, 2019). "Based on this model, we design infusion rates of either insulin (monotherapy) or insulin and glucagon (dual therapy) that can optimally maintain the blood glucose level within desired limits after consumption of a meal and prevent the onset of both hypoglycemia and hyperglycemia." (PMID 30893335, 2019). "The study therefore shows that during hypoglycaemia, glucagon counter-regulation is sustained during DPP-4 inhibition also in the elderly and that there seems to be a glucose threshold between 3.1 and 3.5 mmol/l for the relieve of the inhibition by DPP-4 inhibition of glucagon." (PMID 31275243, 2019). "In addition, it has been reported that hypoglycemia stimulates glucagon secretion by directly elevating cyclic adenosine monophosphate (cAMP) concentrations regardless of Ca2+ signaling." (PMID 31357734, 2019). "As an example of this, the re-expression of Glut2 in astrocytes of Glut2 null mice restores glucagon secretion in response to hypoglycemia, indicating that hypothalamic astrocytes via GLUT-2 are a key part of the central glucose sensing machinery and play a key role in the regulation of glycemia." (PMID 31072002, 2019). "Currently, treatment for severe hypoglycemia is limited to intramuscular injection of a glucagon formulation, which is commercially available as an emergency kit consisting of lyophilized glucagon powder that must be mixed with diluents immediately prior to injection." (PMID 31052466, 2019). "The most novel aspect of the two new models introduced within this work is that they both seek to describe the dynamics between glucose, insulin and glucagon, given that the relationship between glucose and glucagon is key when a patient experiences hypoglycemia." (PMID 31829209, 2019). "Stimulation of insulin production through activation of beta-2 adrenoceptors may also impact glucagon secretion and contribute to reactive hypoglycemia." (PMID 31275775, 2019). "Based on these findings, we can hypothesise that glucagon’s efficacy when used as a rescue treatment in severe hypoglycaemia would be impaired with VLCD." (PMID 31067747, 2019).
Hypoglycemia (continued). "Due to the ease of administration, and also of self-administration, some people may administer IN glucagon to themselves to treat an episode of hypoglycemia before it becomes too serious." (PMID 31349701, 2019). "One might imagine a different scenario, such as, due to the ease of administration, and also of self-administration, some people may administer IN glucagon to themselves to treat an episode of hypoglycemia before it becomes too serious (SH)." (PMID 31349701, 2019). "In the same way that medical students complete requisite basic life support training during their undergraduate medical education, they could participate in a brief training that focuses on hypoglycemia treatment and glucagon administration." (PMID 31138204, 2019). "Patients with longer duration of DM may have experienced more frequent hypoglycemia, which can blunt glucagon and adrenergic responses to hypoglycemia and thus increases patient’s risk to hypoglycemia." (PMID 31651281, 2019). "When GIP levels therefore are elevated, as during DPP-4 inhibition, the glucagon counter-regulation to hypoglycemia may be supported by the action of GIP." (PMID 31275243, 2019). "In addition to hypoglycaemia, stress and cold exposure also act as stimulatory factors for glucagon secretion in lieu of their demand of sustained increase in energy supply during these conditions." (PMID 30505271, 2018). "In addition to glucagon, the counter regulatory responses to insulin-induced hypoglycemia include the increase of various hormones, such as glucocorticoids and catecholamines." (PMID 29880854, 2018). "To test whether FAO contributes to the counter-regulatory response to hypoglycemia in vivo, we measured plasma glucose and glucagon in αCPT1a-KO mice." (PMID 29898400, 2018). "In summary, data from GCK MODY humans were consistent with our hypothesis that GCK-mediated sensing of hypoglycemia contributes to the integrated glucagon and epinephrine counter-regulatory response to a falling blood glucose." (PMID 30146176, 2018). "Co-secretion of glucagon under protein-rich, carbohydrate-poor meals is thought to counteract the simultaneous effects of insulin on blood glucose levels, thus preventing dangerous glucose drops termed “hypoglycemia”8." (PMID 30013127, 2018). "Some findings also revealed that Vildagliptin reduced glucagon during hyperglycemia and maintained its counterregulation during hypoglycemia in T1DM16,17, resulting in reduction in fasting plasma glucose, postprandial plasma glucose, and prevention of hypoglycemia." (PMID 30333575, 2018). "Therefore, future research trails should be designed to carefully identify patients who are most in need of glucagon and show high rates of exercise-induced hypoglycemia." (PMID 30713524, 2018). "Our data support this and indicate that the hypoglycemia in these patients may be caused by a loss of FAO in the α cell and, consequently, reduced glucagon secretion." (PMID 29898400, 2018). "Consistent with our hypothesis, I366F HOM mice showed increased glucagon responses to acute hypoglycemia." (PMID 30146176, 2018). "In this study, the glucagon‐effect appeared right before hypoglycemia occurred." (PMID 29595915, 2018). "Glucagon secretion is promoted during hypoglycemia and inhibited by increased glucose levels." (PMID 29416045, 2018). "This led to an impaired glucagon and epinephrine release during acute hypoglycemia." (PMID 32232085, 2018). "Of note, we did not observe hypoglycemia in the proband despite the increased AGLP-1 levels, which is different from rare patients with GLP-1 and glucagon co-secreting pancreatic neuroendocrine tumor who displayed hyperinsulinemic hypoglycemia and the proliferation of β-cell." (PMID 29556215, 2018).
Hypoglycemia (continued). "It has been suggested that for complete prevention of exercise-induced hypoglycemia, bihormonal systems, involving both insulin and its antagonist, glucagon, may be more successful, as they would better replicate the hormonal changes that usually take place." (PMID 30081478, 2018). "We next tested whether ketone body metabolism could contribute to the maintenance of glucagon secretion in WT islets during hypoglycemia." (PMID 29898400, 2018). "People with lower BMI, perhaps reflecting less availability of hepatic glycogen, may have diminished secretion of glucagon and epinephrine, resulting in inadequate hepatic glucose production during iatrogenic hypoglycemia." (PMID 29473001, 2018). "However, the capacity to release glucagon in response to hypoglycemia was restored by selective re‐expression of GLUT2 in the brainstem glial cells, but not in neurons." (PMID 29274121, 2018). "Modular architecture allows AP systems to be assembled from independent (but compatible) modules, each performing a specific function, e.g. prevention of hypoglycemia, post-meal insulin corrections, fine tuning of basal rate, or administration of ancillary compounds such as amylin or glucagon." (PMID 32232090, 2018). "Our analysis indicates that the paradoxical stimulation of insulin secretion by glucagon minimizes overshoots in blood glucose levels following reversion of hypoglycemia, but has a notable vulnerability - glucose levels drops are accentuated (low minimum after drops)." (PMID 30013127, 2018). "In general, severe hypoglycemia is defined as an episode of low blood glucose where a patient requires assistance of another person to actively administer carbohydrates, glucagon, or take other corrective actions; otherwise, an episode of low blood glucose can be categorized as nonsevere." (PMID 30123259, 2018). "After radiation to this area, hypoglycemia improved, allowing further glucagon titration." (PMID 29340167, 2018). "This indicates a protective effect of glucagon against hypoglycemia." (PMID 29595915, 2018). "Clinical trials with DH-AP may still be conducted with the commercially available glucagon used for severe hypoglycemia treatment but needs to be reconstituted every 24 h." (PMID 30713524, 2018). "Evidence demonstrates that inhibition of in vivo glucagon signaling leads to hypoglycemia." (PMID 28878669, 2017). "Whilst the source of glucagon was previously ascribed to the pancreas, it is difficult to see how the early secretion of glucagon (prior to hypoglycaemia) we have observed, in parallel with GLP-1, might originate from the pancreas." (PMID 28855269, 2017). "In some patients with severe hypoglycemia, both of these scenarios, and others, could lead to impaired glucagon responses to hypoglycemia." (PMID 29259578, 2017). "In patients with longstanding type 1 diabetes, blunting of the glucagon response comes along with the disappearing endogenous insulin production, rendering the patients increasingly dependent upon epinephrine as protection against hypoglycemia." (PMID 28928674, 2017). "Additionally, insufficient glucagon response to hypoglycemia in diabetic patients was shown to be normalized by the maintenance of long-term (1 to 3 months) adequate glycemic control using intensive insulin therapy." (PMID 28426798, 2017). "An early peak in GLP-1 and glucagon may together trigger an exaggerated insulinotropic response to eating and consequent hypoglycaemia in patients with PPH." (PMID 28855269, 2017). "SGLT2 inhibitors have been reported to promote glucagon production, which may limit the likelihood of development of hypoglycemia." (PMID 28785316, 2017). "This inhibition of glucagon secretion may also contribute to the development symptomatic hypoglycemia in these patients." (PMID 29280746, 2017). "However, many patients with T1DM demonstrate impaired response of glucagon and epinephrine to hypoglycemia implicating a possible defect in glucose production during hypoglycemia." (PMID 28570686, 2017).